FPR1 (formyl peptide receptor 1)
Diseases named in the same sentence as FPR1 in open-access papers (continued):
Sharing a sentence is not in itself a finding about the gene and the disease.
COVID-19 (continued). "In this study, we used mRNA-seq data from the peripheral blood of COVID-19 patients to identify six COVID-19 severe immune characteristic genes (FPR1, FCGR2A, TLR4, S100A12, CXCL1, and L TF), and found neutrophils to be the critical immune cells in COVID-19 severe disease." (PMID 38674681, 2024). "Additionally, plasma from COVID-19 patients with mild and moderate/severe symptoms induced in vitro neutrophil activation through fMet/FPR1 (formyl peptide receptor-1) dependent mechanisms (p < 0.0001)." (PMID 37248708, 2023). "scRNA-seq results of COVID-19 find that changes of host factors including EN-RAGE, TNFSF14, oncostatin M, ANXA1, FPR1, and S100A8/9 are correlated with disease severity, revealing the possible pathogenesis of severe COVID-19 and potential host therapeutic targets." (PMID 35495713, 2022). "Furthermore, by integrating the surface target and drug-target binding databases with RNA-sequencing data of severe COVID-19, we identified candidate surface and druggable targets including CCR1 and FPR1 for drug delivery as well as molecular imaging." (PMID 34239034, 2021). "While macrophages in COVID-19 samples expressed chemokines that primarily engage CC and CXC family chemokine receptors on neutrophils (orange box), macrophages in influenza samples expressed ligands that engage formyl peptide receptors (FPR), FPR1 and FPR2 (pink box)." (PMID 34618691, 2021).
gastric cancer (19 papers, 2014 to 2025). A primary or metastatic malignant neoplasm involving the stomach. "High expression of FPR1, associated with an aggressive tumor phenotype and poor patient survival, has been observed in gastric cancer, neuroblastoma, melanoma, and astrocytoma." (PMID 40733247, 2025). "FPR 1 over-expression has been shown to be associated with tumor progression and survival in gastric cancer, indicating a link between FPR1-mediated pro-inflammatory cascades and poor outcome in cancer patients." (PMID 31116781, 2019). "For instance, in gastric cancer a high expression of FPR1was associated with advanced disease and poor survival, while another study reported FPR1 to be a tumor suppressor by inhibition of angiogenesis." (PMID 27432059, 2016). "We recently showed that the genetic ablation of FPR1 caused an increase in proinflammatory, angiogenic and tumorigenic potential in gastric cancer (GC) cells." (PMID 35808840, 2022). "In addition, Fpr1 SNP (rs1042229) was also associated with stomach cancer." (PMID 32284754, 2020). "We identified FPR1 as a tumour suppressor in gastric cancer cells due to its ability to sustain an inflammation resolution response with antiangiogenic potential." (PMID 35808840, 2022). "We recently demonstrated that the innate immune receptor FPR1 is crucial in gastric cancer (GC) to sustain the constitutive production of pro-resolving mediators that restrains tumor growth by suppressing angiogenesis." (PMID 33578955, 2021). "One rather interesting property of FPR1 was to inhibit the progression of gastric cancer as a potential “tumor suppressor”." (PMID 32038501, 2020). "The expression of FPR1 in gastric cancer tissue is higher than that in normal tissue and is closely related to the survival time of the patient, and FPR2 is also highly expressed in endometrial cancer and colon cancer." (PMID 33679387, 2020). "In conclusion, CTHRC1 expression may induce tumor associated macrophage infiltration though GRN/TNFRSF1A and AnxA1/FPR1 pathways and also tumor angiogenesis in gastric cancer." (PMID 35928443, 2022). "The discovery that innate immune receptors (i.e., FPR1 in gastric cancer and TLR7 in lung cancer) might control PUFA metabolism, inflammation resolution, angiogenesis, and cancer opens new possibilities to be exploited for cancer treatment." (PMID 33578955, 2021). "We should however note that in gastric cancer the role of FPR1 remains ambiguous." (PMID 33057069, 2020). "In addition, CTHRC1 expression may induce tumor associated macrophage infiltration though GRN/TNFRSF1A and AnxA1/FPR1 pathways and also tumor angiogenesis in gastric cancer." (PMID 35928443, 2022). "With the aim to study the role of PRRs in the context of cancer, we recently demonstrated that a specific PRR, namely FPR1, functions as a tumor suppressor in gastric cancer (GC) by activating pro-resolving pathways and suppressing angiogenesis." (PMID 33578955, 2021). "The most potent compounds in this series (24a and 25b) were selected to study the effects of the pharmacological blockade of FPR1 in NCl–N87 and AGS gastric cancer cells." (PMID 37839346, 2023). "Furthermore, in human gastric cancer (GC), FPR1 levels are correlated with more aggressive submucosal and serosal invasion accompanied by worse outcomes in patients." (PMID 33804219, 2021). "We first aimed to evaluate the role of TLR7 in NSCLC cells, paying particular attention to its impact on tumor angiogenic potential in order to verify whether its role is similar to that of FPR1 in gastric cancer (GC)." (PMID 33578955, 2021). "We demonstrated that a specific PRR—formyl peptide receptor 1 (FPR1)—sustains an inflammation resolution response with anti-angiogenic and antitumor potential in gastric cancer." (PMID 33578955, 2021).
gastric cancer (continued). "Aberrant expression of FPR1 has been detected in various adult cancers and increased expression of FPR1 in tumors has previously been reported as a negative prognostic factor in patients with gastric cancer, astrocytoma and melanoma." (PMID 27432059, 2016). "For example, FPR1 exerts a tumor suppressor function in gastric cancer (GC) by inhibiting angiogenesis, while FPR2 has been reported to contribute to tumor progression by promoting invasion and metastasis of GC cells." (PMID 36120322, 2022).
breast carcinoma (18 papers, 2017 to 2025). "Single nucleotide polymorphisms that suppress FPR1 signaling are associated with decreased survival in patients receiving adjuvant chemotherapy for breast cancer, suggesting that FPR1 is important for the antitumor immune response to chemotherapy." (PMID 34638242, 2021). "At clinical level the data collected correlated with the fact that patients that were heterozygous carriers of the FPR1 loss-of-function allele manifested a poor prognosis after anthracycline-based breast cancer chemotherapy." (PMID 28986543, 2017). "Survival analysis showed that the over-expression of GPR37 and the down-regulation of FPR1 were associated with poor overall survival in breast cancer patients, indicating that these hub genes may potentially be a driver for breast cancer development." (PMID 35045088, 2022). "Other limitations to boost anticancer immunity in cancer patients via AnxA1 administration include the high prevalence of a loss-of-function FPR1 allele common in all ethnic groups, which is associated with poor prognosis, at least in breast cancer patients, after anthracycline-based chemotherapy." (PMID 33810523, 2021). "All in all, our work provides mechanistic insights into how microglia, in the brain tumor microenvironment, respond to metastatic breast cancer cells through activation of FPR1/2-STAT3 axis, driven by ANXA1 paracrine/autocrine loop." (PMID 35382852, 2022). "The AnxA1/FPR1 autocrine axis can promote invasiveness in breast cancer." (PMID 40538442, 2025). "In addition, Vecchi has reported that inhibiting AnxA1/FPR1 autocrine axis can reduce breast cancer cell growth and aggressiveness both in vitro and in vivo." (PMID 35928443, 2022). "Implicit in the disconnection between the two observations (treatment of BV-2 microglial cells with ΔANXA1 4T1 CM versus 4T1 CM with FPRs antagonists) is the interpretation that FPR1/2 was still activated despite genomic deletion of ANXA1 in 4T1 metastatic mammary cancer cells." (PMID 35382852, 2022). "Adding further complexity, secretion of AnxA1 from TNBC cells might induce autocrine signalling via FPR1 to further increase breast cancer cell aggressiveness and survival and could be blocked with cyclosporin A, a FPR1 inhibitor." (PMID 33810523, 2021). "Consequently, overall survival of patients with breast cancer with tumors exhibiting high RNA expression of FPR1 or CXCR4 was more impaired than that of patients with low tumor RNA expression of these molecules." (PMID 34876407, 2021). "We test our approach on a cell coculture where leukocytes, carrying or not a genetic polymorphism for FPR1, interact with human chemotherapy treated breast cancer cells." (PMID 28986543, 2017). "Furthermore, the optimal FK4‐RuAvi transporter showed excellent anticancer effects on FPR‐1 overexpressing MDA‐MB‐231 breast cancer cells both in 2D monolayer and 3D spheroid cell culture, suggesting that it could penetrate effectively and generate ROS to induce cell death upon laser irradiation." (PMID 40129407, 2025). "We here confirmed that B16F10 cells constitutively express FPR1 and FPR2, and data from the literature show that AnxA1 binds to both receptors and leads to cancer progression, such as breast cancer." (PMID 36766767, 2023). "Protein-protein interaction (PPI) analysis revealed seven shared (PLCB1, FPR1, FPR2, CX3CL1, GABBR2, GPR37, and CXCR4) hub genes between brain and lung metastasis in breast cancer." (PMID 35045088, 2022). "There were seven shared hub nodes (FPR2, CXCR4, FPR1, CX3CL1, GPR37, GABBR2 and PLCB1) between metastatic breast cancer cell lines." (PMID 35045088, 2022).
glioma (18 papers, 2010 to 2026). A benign or malignant brain and spinal cord tumor that arises from glial cells (astrocytes, oligodendrocytes, ependymal cells). "The fact that FPR1 is abundantly expressed in gliomas and other cancer cells in combination with the observation that activation of FPR1 stimulates receptor-mediated endocytosis, makes it a highly attractive target for radiopharmaceutical development." (PMID 40940450, 2025). "Studies of human primary glioma specimens demonstrate the co-expression of FPR1 and Anx A1 in more highly progressive tumors indicating the clinical relevance of the receptor and a tumor-derived ligand." (PMID 32038501, 2020). "A substantial body of work has already shown that the expression of FPR1 is elevated in glioma, and that the expression correlates with the stage of tumours." (PMID 33057069, 2020). "Therefore, further investigation of ICT12035, or other FPR1 antagonists, can open opportunities for more efficient treatment for cancers, including glioma, in due course." (PMID 33057069, 2020). "Furthermore, to show the relevance of necrosis to the FPR1-mediated expansion of gliomas, we used ICT12035 to retard increases in both proliferation and invasion of U87 spheroids as well as monolayers by necrotic U87 supernatants." (PMID 33057069, 2020). "In addition early passage Groningen Glioma (GG) cells were screened for functional FPR1 expression and presence of FPR1 mRNA." (PMID 25894595, 2015). "However, ANXA1 expression is upregulated in malignant glioma tissues; it is secreted by necrotic glioma cells, and abnormal levels of ANXA1 in the tumour microenvironment can activate formyl peptide receptor 1 to enhance the proliferation and invasion of glioma." (PMID 35415239, 2022). "We set out to provide the proof of the principle that a small molecule FPR1 antagonist, such as ICT12035, can have a potential as a therapy for cancers such as glioma." (PMID 33057069, 2020). "In glioma, the Formyl peptide receptor (FPR, also called FPR1) can regulate the invasion, angiogenesis and growth of tumor, however, the function of FPR3 in glioma is still unclear." (PMID 33408717, 2020). "At a non-cytotoxic concentration, F2 selectively suppressed the function of FPR1 (formyl peptide receptor 1) and the FPR1-mediated signaling pathway in a manner of a partial agonist in U87 cells, and it also inhibited the HIF-1 pathway in U251 glioma cells." (PMID 29156717, 2017). "Eight early passage human Groningen Glioma (GG) cell lines, isolated from primary GBM tissue were screened for the presence of FPR1." (PMID 25894595, 2015). "Interestingly, we found that FPR1 expression increased with tumor grade, with marginal evidence of expression in lower grade II and III gliomas and strong evidence of expression in grade IV." (PMID 35619544, 2022).
colorectal cancer (14 papers, 2017 to 2025). A primary or metastatic malignant neoplasm that affects the colon or rectum. "In this study, we investigated the single nucleotide polymorphisms (SNPs) of Fpr1 in human colorectal cancer (CRC), and analyzed the association of Fpr1 SNPs with clinicopathological parameters and some specific diagnostic markers of CRC." (PMID 32284754, 2020). "In summary, our studies have, for the first time, demonstrated that the expression of FPR1 is associated with tumor invasion of colorectal cancer." (PMID 28724995, 2017). "Finally, genetic deletion of fpr1 increased the survival rate of the resulting knockout mice compared with wild type littermates in a mouse model of colitis-associated colorectal cancer." (PMID 28724995, 2017). "In addition, a variant rs867228 (minor allele frequency = 0.21) producing a loss-of-function allele in FPR1 is associated with poor metastasis-free and overall survival in breast and colorectal cancer patients receiving adjuvant chemotherapy." (PMID 28793908, 2017). "Ye has shown that FPR1-/- mice have increased survival compared with FPR+/+ littermates in a colorectal cancer model." (PMID 33057069, 2020). "Constitutional loss of function (LOF) single nucleotide polymorphisms (SNPs) in pattern recognition receptors FPR1, TLR3, and TLR4 have previously been reported to predict oxaliplatin benefit in colorectal cancer." (PMID 30649440, 2019). "Furthermore, the knockout of the FPR1 gene in mice increased the survival rate in a model of colorectal cancer, and it was also found that the receptor was expressed at significantly higher levels in tumor tissues than in normal tissues." (PMID 40733247, 2025). "Additionally, these Fpr1-/- mice were highly prone to developing chronic ulcerative colitis and colorectal cancer when exposed to the mutagen azoxymethane followed by dextran sodium sulfate, which induces colitis." (PMID 40733247, 2025). "To determine whether FPR1 activates a proresolving program also in colon cancer, we selected two human colorectal carcinoma (CRC) cell lines, HT29 and HCT116 cells." (PMID 35808840, 2022). "Taken together, these results suggested a close correlation between FPR1 expression and colorectal cancers while FPR2 expression might be more sensitive in the colon cancer and affects the invasive phenotype of human colon cancer more specifically." (PMID 28724995, 2017). "Furthermore, we confirm the function of FPR1 on tumor migration and invasion using chemotaxis and wound-healing assays in two colorectal cancer cell lines." (PMID 28724995, 2017). "Here, we investigate whether FPR1 exerts similar functions in colorectal carcinoma (CRC) cells." (PMID 35808840, 2022). "Likewise, formyl peptide receptor 1 (FPR1) facilitates inflammation-mediated angiogenesis and immune regulation in gastric and colorectal cancers." (PMID 40994571, 2025). "However, the function of Fpr1 SNPs in human colorectal cancer has not been investigated." (PMID 32284754, 2020).
colitis (12 papers, 2012 to 2025). Inflammation of the colon. "There were similarities in the phenotype among Fam3D−/−, Fpr2−/−, and Fpr1/2−/− mice, and mice deficient in another Fpr2 agonist Cramp in that they all showed increased susceptibility to chemically induced colitis." (PMID 33219235, 2020). "Finally, we demonstrated that the expression of FPR1 is correlated with the survival of colitis-associated CRC mice." (PMID 28724995, 2017). "In light of evidence that exogenous fMLF enhances colonic neutrophil infiltration during induced colitis and that the neutrophils of patients with inflammatory bowel disease possess increased numbers of FPR1, we thought it interesting to examine FPR1 gene-deficient mice with DSS-induced colitis." (PMID 22383080, 2012). "In a colitis-induced model, fpr1-null mice exhibited decreased leukocyte migration into the inflamed gut." (PMID 40733247, 2025). "Another report showed that Fpr1 deletion elicits decreased leukocyte migration into the inflamed intestine in a trinitrobenzene sulfonic acid-induced colitis model." (PMID 33082511, 2020). "FPR1 is abundantly expressed on neutrophils and macrophages and stimulates their migration into the mucosa and lumen in response to formyl peptides generated from resident bacteria during the development of colitis." (PMID 36248794, 2022). "Our data showed that the absence of FPR1 could increase the survival rate of fpr1−/− mice compared with WT mice in a mouse model of colitis-associated CRC, suggesting that FPR1 expression is a risk factor in the prognosis of CRC." (PMID 28724995, 2017). "In DSS-induced colitis, neutrophil migration is induced by other chemokines, such as CXCL2, and FPR1 affects the resolution and recovery of the intestinal barrier." (PMID 33082511, 2020). "Given the abundance of neutrophils in the inflamed colon, our aim was to determine if the FPR1 mediates colonic neutrophil migration, using the dextran sodium sulfate (DDS)-induced model of colitis." (PMID 22383080, 2012). "A curative role of FPR1 has been demonstrated in experimental colitis in mice, but not in human experiments." (PMID 40540498, 2025). "And in the colitis model of mice, it has been indicated that there was reduced NF-κB translocation into the nucleus in absence of the FPR-1 gene." (PMID 33981222, 2021). "Despite the lack of a major chemotactic receptor, neutrophils with Fpr1 knockout can still migrate into inflamed intestinal mucosa in the dextran sulfate sodium (DSS)-induced colitis model." (PMID 33082511, 2020). "The data lead us not only to this conclusion, but also to the conclusion that the lack of FPR1 offers some protection from DSS colitis in the acute setting independent of neutrophils." (PMID 22383080, 2012). "If DSS colitis is neutrophil independent, then the FPR1 must have roles in colon pathology independent of neutrophils." (PMID 22383080, 2012). "Annexin A1 levels increase during DSS colitis, with the molecule acting through the FPRL1; however, we speculated that mucosal levels of annexin A1 might be upregulated by signals through the FPR1 acting as a sensor for invasive bacteria." (PMID 22383080, 2012).